IGF2BP1 (insulin like growth factor 2 mRNA binding protein 1)
Diseases named in the same sentence as IGF2BP1 in open-access papers (continued):
Sharing a sentence is not in itself a finding about the gene and the disease.
tumor (continued). "Consistently, the elevated level of IGF2BP1 protein was noted in 12 pairs of tumor tissues than those of adjacent non-cancerous tissues." (PMID 33853613, 2021). "The m6A reader protein IGF2BP1 could activate SRF-dependent transcription and thus endorse tumor cell growth in an m6A-dependent manner in ovarian, liver, and lung cancers." (PMID 34149792, 2021). "The increased expression of IGF2BP1 in primary tumor parts was observed regardless of metastatic status (p < 0.001) in HCMDB analysis." (PMID 34203267, 2021). "In HCC cells, several studies showed that the miR-29-3p-family acted as tumor-suppressive miRNAs via negative control of several oncogenic targets, e.g., IGF2BP1, RPS15A and LOXL2." (PMID 34199886, 2021). "Specifically, by promoting the expression of serum response factor (SRF) in an m6A-dependent manner via impairing the miRNA-dependent decay of the SRF mRNA, IGF2BP1 promotes SRF-dependent transcription in cancer, thereby enhancing tumor cell growth and invasion." (PMID 34692544, 2021). "In addition, the family of RNA-binding proteins insulin-like growth factor 2 mRNA-binding proteins (IGF2BP1, 2, 3) regulates IGF2 transcript stability at post transcriptional level by modulating IGF2 production in embryos and tumor cells." (PMID 34440844, 2021). "As a conservative oncogenic driver network, IGF2BP1 promotes SRF expression in a conservative, m6A-dependent manner by inhibiting miRNA-induced SRF mRNA decay, leading to enhanced transcriptional activity of SRF, promoting tumor cell growth and invasion." (PMID 33552994, 2020). "Furthermore, the expression of IGF2BP1, METTL3 and METTL14 is strongly correlated with E2F1–3 expression (R = 0.4) across 33 TCGA tumor cohorts." (PMID 32761127, 2020). "Consistent with in vitro experiments, in vivo tumours derived from TCam‐2/CDDP cells with METTL3 overexpression grew more rapidly than negative control under CDDP treatment and the growth was inhibited by IGF2BP1 inhibition." (PMID 32857912, 2020). "The severe inhibition of tumor growth and peritoneal spread by BTYNB demonstrated in experimental tumor models provides strong, pre-clinical evidence that the therapeutic inhibition of IGF2BP1 is feasible." (PMID 32761127, 2020). "Moreover, IGF2BP1 stabilizes the mRNA of SRF to promote its expression, leading to enhanced expression of oncogene FOXK1 and PDLIM7 in tumor cells, and a more aggressive phenotype." (PMID 32950970, 2020). "This was confirmed in additional tumor-derived cell lines (data not shown) demonstrating that the IGF2BP1-dependent upregulation of SRF expression is highly conserved in cancer cells." (PMID 30371874, 2019). "For example, IGF2BP1 expression might upregulate RGS4 mRNA and inhibit tumor cell proliferation and invasion, while downregulate GDF15, IGF2, and PTG2 mRNAs and lead to suppression of tumor cell proliferation and invasion." (PMID 29954406, 2018). "Our study suggests that miR-9 functions as a tumor suppressor in HCC progression by inhibiting a series of target genes, including the newly validated miR-9/IGF2BP1/AKT&ERK axis, thus providing potential therapeutic targets and novel prognostic biomarkers for HCC patients." (PMID 26547929, 2015). "The expression levels of ONECUT2, IGF2BP1, and ANXA2 were significantly upregulated in tumor tissues compared with non-tumor tissues, which suggested that they might play an oncogenic role in HCC development." (PMID 26547929, 2015). "The result confirmed that the expression levels of ONECUT2, IGF2BP1, and ANXA2 were significantly elevated in non-tumor tissues compared to normal tissues (P = 0.0116, P = 0.0380 and P = 0.0145, respectively), and further elevated in HCC tissues (P = 0.0270, P = 0.0003 and P < 0.0001, respectively)." (PMID 26547929, 2015). "This provided further evidence for an essential function of IGF2BP1 in inducing and/or sustaining mesenchymal-like properties in various, although not all, mesenchymal-like tumor cells." (PMID 23677615, 2013).
tumor (continued). "Hence, in tumor-derived cells still expressing functional PTEN, IGF2BP1 can enhance both the speed and the directedness of cell movement." (PMID 23069990, 2013). "Thus, the pro-survival role of IGF2BP1 and IGF2BP3 in response to these therapeutic treatments in vitro suggests that IGF2BPs also serve a role in mediating chemo-/radio-resistance of tumor cells." (PMID 23069990, 2013). "This suggests LEF1 as a prime, although not exclusive candidate, through which IGF2BP1 promotes mesenchymal-like tumor cell properties." (PMID 23677615, 2013). "Furthermore, the CNV of IGF2BP1/2/3 showed a positive correlation with mRNA expression in most tumor types, while a negative correlation was observed in BRCA, CESC, COAD, KIRC, and LIHC." (PMID 40088376, 2025). "Furthermore, previous studies had shown that miR-98-5p could target IGF2BP1 and IGF2BP2 to regulate tumor cell growth." (PMID 40530014, 2025). "Similarly, Insulin-like growth factor-2 mRNA-binding proteins (IGF2BP1/2/3) have been found to be overexpressed in AML, and to regulate the stability of specific mRNAs, including MYC, in an m6A-dependent manner to promote tumor progression." (PMID 39085650, 2024). "IGF2BP1 promotes SRF expression in a conservative m6A-dependent manner by impairing the decay of SRF mRNA guided by miRNA, thereby promoting the expression of genes such as PDLIM7 and FOXK1 that can promote tumor cell growth, ultimately promoting tumor cell growth and invasion." (PMID 39062595, 2024). "Furthermore, small molecule inhibitors of IGF2BP1 function, including BTYNB or Cucurbitacin B, that have recently shown promising anti-tumor effects, should be tested for their impact on the production and infectivity of the virus species reported to benefit from IGF2BP1 expression." (PMID 37515119, 2023). "Apart from neoplastic diseases, IGF2BP1 also plays a crucial role in nonneoplastic diseases." (PMID 36632449, 2023). "Hence, IGF2BP1 upregulated fibronectin and CD45+ cell infiltration, suggesting the role of IGF2BP1 in EV-enhanced metastasis and preparing the metastasis niche for the easier homing of NB tumour cells." (PMID 37887559, 2023). "Our findings suggest that IGF2BP1 is an independent predictor and related to immunotherapy response in LUAD, which maybe a potential novel biomarker for LUAD prognosis and the status of tumor immunity." (PMID 35154270, 2022). "However, we found YTHDC1, ZCCHC4, IGF2BP1 were not differently expressed between normal and tumor samples." (PMID 33748145, 2021). "Moreover, based on in vivo results, shIGF2BP1 alone reduced tumor growth, but shPTPN13 did not affect tumor growth after IGF2BP1 silencing compared with control IGF2BP1 expression." (PMID 33051595, 2021). "Functionally, the LINC00261 overexpression-induced cell proliferation and glycolysis suppression, apoptosis acceleration, and cell cycle arrest could be reversed by IGF2BP1 overexpression, suggesting that IGF2BP1 was necessary for LINC00261 to exert its tumor suppressive function." (PMID 33122827, 2021). "In hepatocellular carcinoma, IGF2BP1 can bind and stabilize c-MYC and MKI67 mRNAs, increase the expression of c-MYC and MKI-67 proteins, which are effective regulators of cell proliferation and apoptosis, and thus participate in regulation of tumor progression." (PMID 33552994, 2020). "Besides, immunochemistry analysis showed that ACLY expression was evidently decreased in the tumor tissues of IGF2BP1 knockout group or NONO knockout group, compared to that in control group." (PMID 32884448, 2020). "Despite the obvious, cell type-dependent and variable extent of IGF2BP1/SRF-directed regulation, the presented findings suggested that IGF2BP1 and SRF exhibit similar effects on promoting a pro-proliferative and pro-invasive gene expression signature in tumor cells." (PMID 30371874, 2019).
tumor (continued). "Additionally, IGF2BP1 prevents CD44 and PTEN mRNA turnover, consequently enhances CD44 expression, and induces the formation of invadopodia and therefore may promote tumor cell migration and invasiveness." (PMID 29954406, 2018). "Importantly, in none of the analyzed tumor-derived cells, IGF2BP1 depletion was sufficient to induce upregulation of epithelial markers to a level expected for MET." (PMID 23677615, 2013). "However, the stable expression of IGF2BP1 in epithelial-like MCF7 tumor-derived cells or kidney-derived MDCK cells failed to induce EMT or a significant upregulation of mesenchymal marker expression." (PMID 23677615, 2013). "Therefore, we addressed how perturbing IGF2BP1 expression in tumor-derived cells and non-tumorigenic HEK293 cells, which express exceedingly high levels of IGF2BP1, affects mesenchymal- versus epithelial-like cell properties." (PMID 23677615, 2013). "However, in epithelial-like tumor-derived cells characterized by a lack or low abundance of IGF2BP1, the protein fails to induce EMT." (PMID 23677615, 2013). "Furthermore, a study using HCC revealed that IGF2BP1 knockdown can remarkedly increase the infiltration of immune cells, including CD8+ T cells, CD4+ T cells, F4/80+ macrophage, and CD56+ natural killer cells, thereby decreasing PD-L1 expression level and activating tumor immune microenvironment." (PMID 40584294, 2025). "As the IGF2BP1-driven malignant phenotypes observed in clinical specimens may have resulted from intercellular interactions between IGF2BP1-expressing CRC cells and neighboring host cells within a tumor microenvironment (TME) or IGF2BP1-experssing CRC cells alone." (PMID 34203267, 2021). "However, determining whether the occurrence of tumor events or not partly depends on IGF2BP1 targeting different cancer-related mRNAs, although the driving factors that contribute to this gene to choose different mRNA targets are unclear." (PMID 29954406, 2018). "In syngeneic LUAD xenografts in mice, IP injection of AVJ16 prevents tumor growth, and incubation with AVJ16 induces cell death in human organoids derived from IGF2BP1-expressing LUADs but not from healthy lung tissue." (PMID 40629079, 2025). "Strong oncogenic synergy of MYCN/IGF2BP1 is evidenced in R26IGF2BP1/MYCN mice, showing reduced tumor latency without or mild chromosomal disturbance." (PMID 37246217, 2023). "IGF2BPs, particularly IGF2BP1 and IGF2BP3, are widely recognized as oncofetal proteins predominantly expressed in cancer rather than normal tissues, playing a critical role in tumor initiation and progression." (PMID 37280679, 2023). "CLIC5 and IGF2BP1 have been identified as markers of hyperdiploid ALL, however, none of the test tumours used in this analysis were hyperdiploid." (PMID 34753926, 2021). "Overall, these results indicate that IGF2BP1 and NONO are frequently upregulated in HCC tissues and promote tumor masses." (PMID 32884448, 2020). "In glioblastoma-derived tumor-cells lacking PTEN, IGF2BP1 was found to exclusively promote the speed but not the directedness of random migration." (PMID 23069990, 2013). "Based on these published data and our observations, IGF2BP1 could be a very promising target for ESCC, making it possible to specifically target tumor cells without disturbing noncancerous tissues." (PMID 37644505, 2023). "However, the protein expression of IGF2BP1 and VIRMA in the normal control group and tumor group was not consistent with the mRNA expression levels." (PMID 32950970, 2020). "Hence, although IGF2BP1 failed to induce EMT and sustained the expression of mesenchymal markers only moderately, the post-transcriptional fine tuning of gene expression facilitated by IGF2BP1 is sufficient to substantially impact cell morphology and tumor cell migration." (PMID 23677615, 2013).
cancer (230 papers, 2007 to 2025). A tumor composed of atypical neoplastic, often pleomorphic cells that invade other tissues. "In general, IGF2BP1’s expression in numerous types of cancers is associated with upregulation of key pro-oncogenic RNAs, poor prognosis, and reduced survival." (PMID 40629079, 2025). "IGF2BP1 is frequently overexpressed in various types of cancer and is associated with poor prognosis." (PMID 40584294, 2025). "In this review, we summarize the current research regarding the biological roles of IGF2BP1 and the underlying molecular mechanisms by which IGF2BP1 regulates cancer hallmarks." (PMID 40584294, 2025). "Our results showed that, the expression of m6A regulators was associated with subgroup differentiation in six of these cancer types, with the IGF2BP1/2/3 family emerging as a key factor in defining these subgroups." (PMID 41049442, 2025). "As previously shown, IGF2BP1–3 also targeted other genes that participate in several mechanisms associated with an increased cell proliferation rate, potentially promoting cancer progression." (PMID 40918643, 2025). "This review summarizes the current knowledge on the functional roles and underlying molecular mechanisms of IGF2BP1 in regulating cancer hallmarks." (PMID 40584294, 2025). "Next, to further elucidate the role of IGF2BP1 in cancer progression, we examined its association with cancer-related pathways and its impact on the sensitivity to common chemotherapeutic agents." (PMID 39512352, 2024). "Recent studies have shown that IGF2BP1 dependent mRNA encode oncoproteins that are essential for neoplastic transformation and cancer cell progression." (PMID 38166832, 2024). "In a large member of cancers, IGF2BP1 has been demonstrated to be highly expressed and facilitate the processes of cancers by modulating RNA molecules associated with cancer development." (PMID 38129874, 2023). "Elevated IGF2BP1 expression has been implicated in the development and progression of various cancers in, e.g., ovary, lung, pancreas, liver and breast and is typically associated with poor prognosis." (PMID 37515119, 2023). "IGF2BP1 is de novo expressed in several cancers and shows conserved association with poor prognosis, disease progression and metastasis." (PMID 37246217, 2023). "High-risk genes (C1QTNF6, LDHA, IGF2BP1) resulted in poor clinical outcomes by promoting cancer cell metabolism and proliferation." (PMID 36032673, 2022). "This direct m6A-dependent stabilization of EZH2 mRNA by IGF2BP1 further underlines its oncogenic role in cancer, which so far has mainly been attributed to its inhibitory action on miRNA/RISC-directed downregulation of antiproliferative target mRNAs." (PMID 35565249, 2022). "Igf2bp1 is an oncofetal RNA binding protein whose expression in numerous types of cancers is associated with upregulation of key pro-oncogenic RNAs, poor prognosis, and reduced survival." (PMID 34895045, 2022). "In this study, we present a set of genes and cancer hallmark pathways showing a conserved pattern of deregulation in dependence of IGF2BP1 expression in cancer cell lines." (PMID 33829040, 2021). "Collectively, this emphasizes a broad, multilayered role of IGF2BP1 in promoting key cancer hallmark pathways like MYC/N- and E2F-driven gene expression." (PMID 33829040, 2021). "In conclusion, our studies reveal a potent analysis pipeline for the identification of conserved, pro-oncogenic effectors and hallmark pathways regulated by IGF2BP1 in cancer." (PMID 33829040, 2021). "In the here presented study we present an analysis pipeline for the identification of conserved cancer hallmark pathways influenced by IGF2BP1 by stabilizing target mRNAs encoding pro-oncogenic factors." (PMID 33829040, 2021). "All three novel candidate target mRNAs showed consistent downregulation in the investigated cancer cell models upon IGF2BP1 knockdown and their RNA expression was positively associated with IGF2BP1 expression across solid cancers." (PMID 33829040, 2021).
cancer (continued). "This information allows pursuing the evaluation of targetable IGF2BP1 effectors to test the potential benefit of inhibiting IGF2BP1-RNA association and combined treatment with effector inhibition in cancer therapy." (PMID 33829040, 2021). "The main role proposed for IGF2BP1 in cancer cells is the stabilization of mRNAs encoding pro-oncogenic factors." (PMID 33829040, 2021). "Gene set enrichment analyses (GSEA) of candidate target mRNA of IGF2BP1 support a pivotal role of the protein in cancer cell cycle progression, but furthermore highlight cancer hallmark pathways influenced by IGF2BP1." (PMID 33829040, 2021). "These analyses confirm a pivotal role of IGF2BP1 in controlling cancer cell cycle progression and reveal novel cancer hallmark pathways influenced by IGF2BP1." (PMID 33829040, 2021). "Future studies will have to reveal the potential benefit of combined inhibition of IGF2BP1-RNA association and pro-oncogenic factors enhanced by IGF2BP1 in cancer cells in a conserved manner." (PMID 33829040, 2021). "By the integrative analysis of these findings with publicly available cancer transcriptome and IGF2BP1-RNA association data, we compiled a set of prime candidate target mRNAs." (PMID 33829040, 2021). "The loss of IGF2BP1 inhibits Cdc34, Lin-28B, and K-Ras, suppresses cancer cell proliferation and anchorage-independent growth, and promotes caspase-mediated cell death." (PMID 34203267, 2021). "Nonetheless, we present evidence that BTYNB impairs IGF2BP1-dependent stabilization of mRNAs encoding factors, which promote cell cycle and cancer progression." (PMID 32761127, 2020). "These genes also showed significant and concise association with IGF2BP1 expression in the five respective primary cancers." (PMID 32761127, 2020). "IGF2BP1-dependent mRNAs encode oncogenic proteins, essential for neoplastic transformation and cancer cell progression." (PMID 32917856, 2020). "Like observed for IGF2BP1, the mRNA expression of the 31 identified E2F/IGF2BP1-driven factors was associated with a significantly reduced survival probability across 33 cancers." (PMID 32761127, 2020). "For 9 out of 33 cancers, high IGF2BP1 mRNA expression was significantly (P < 0.05) associated with adverse prognosis." (PMID 32761127, 2020). "Clinical association analysis revealed that higher expressions of IGF2BP1/2/3 were associated with worse survival of cancer patients." (PMID 33575259, 2020). "IGF2BP1 presents an exception of an m6A-binding RBP with a documented effect on a cancer-associated lncRNA, namely the ~500-nt-long lncRNA highly up-regulated in liver cancer (HULC)." (PMID 32340118, 2020). "The majority of transcripts enhanced by SRF/IGF2BP1 in ES-2 cells show a conserved association with SRF/IGF2BP1-expression in cancer." (PMID 30371874, 2019). "This suggested that potentially ‘oncogenic’ effectors of SRF/IGF2BP1 are identified by a conserved positive association with SRF/IGF2BP1-expression in cancer and downregulation upon SRF and IGF2BP1 depletion in cancer-derived cells." (PMID 30371874, 2019). "Although SRF-promoter and IGF2BP1-3′UTR association appeared conserved for only 257 of 539 DN-transcripts, the vast majority of these mRNAs showed positively associated expression with SRF and IGF2BP1 in the four cancers analyzed." (PMID 30371874, 2019). "Until recently, functional studies have emerged to find out the underling mechanism of IGF2BP1 involved in cancers." (PMID 27588393, 2016). "Expression of IGF2BP family members has been implicated in various cancers; however, the vast majority of reports consider exclusively IGF2BP1 and IGF2BP3." (PMID 23069990, 2013). "Furthermore, up-regulated IGF2BP1 expression is frequently found in a broad range of cancers, and is associated with poor prognosis." (PMID 40584294, 2025). "To determine whether known targets of LIN28A/LIN28B would be able to rescue cancer initiation in Lin28a/Lin28b-deficient mice, we tested Igf2bp1, Igf2bp2, and Igf2bp3." (PMID 38875287, 2024).